RCBTB2 (RCC1 and BTB domain containing protein 2)
Synonyms: CHC1L; RLG
Tractability: PROTAC: ubiquitination databases record sites on it; its protein half-life has been measured.
Gene: Protein-coding gene on chromosome 13 (48,488,959 to 48,536,006, reverse strand). Ensembl gene ENSG00000136161.
Subcellular location: Cytoplasmic vesicle, secretory vesicle, acrosome
Subcellular location (Human Protein Atlas): Golgi apparatus; Nucleoplasm
Gene Ontology:
Molecular function: protein binding; guanyl-nucleotide exchange factor activity
Cellular component: cytoplasm; acrosomal vesicle
Genetic constraint (gnomAD): Loss-of-function variants: 52 observed, 60.65 expected, observed/expected ratio (o/e) 0.86, 90% interval 0.69 to 1.08. The upper end of that interval is the gene's LOEUF score, 1.08, which puts it in group 4 of 6, group 1 being the genes least tolerant of losing a copy. Missense variants: 564 observed, 669.45 expected, observed/expected ratio (o/e) 0.84, 90% interval 0.79 to 0.9. Synonymous variants: 211 observed, 251.84 expected, observed/expected ratio (o/e) 0.84, 90% interval 0.75 to 0.94.
Homologues: Orthologues: chimpanzee RCBTB2 (98% identical), macaque RCBTB2 (97% identical), rabbit RCBTB2 (95% identical), guinea pig RCBTB2 (95% identical), mouse Rcbtb2 (95% identical), pig RCBTB2 (95% identical), rat Rcbtb2 (95% identical), dog RCBTB2 (95% identical), tropical clawed frog rcbtb2 (76% identical), zebrafish rcbtb2 (72% identical), Drosophila melanogaster ca (21% identical), Caenorhabditis elegans ran-3 (14% identical), and 2 more. Paralogues in human: RCBTB1 (67% identical), RPGR (23% identical), SERGEF (21% identical), HERC1 (20% identical), RCC1L (19% identical), RCC2 (19% identical), ALS2 (18% identical), RCC1 (14% identical), RCCD1 (10% identical).
Diseases named in the same sentence as RCBTB2 in open-access papers:
RCBTB2 is named in the same sentence as 15 diseases in open-access papers, as found by Europe PMC text mining. Sharing a sentence is not in itself a finding about the gene and the disease. The quoted sentences say what the papers report.
prostate carcinoma (4 papers, 2015 to 2024). A carcinoma that arises from epithelial cells of the prostate gland. "Ross-Adams and his co-workers demonstrated that the RCBTB2 gene, in addition to the other five genes, was associated with prostate cancer." (PMID 38612439, 2024). "We confirm alterations in six genes previously associated with prostate cancer (MAP3K7, MELK, RCBTB2, ELAC2, TPD52, ZBTB4), and also identify 94 genes not previously linked to prostate cancer progression that would not have been detected using either transcript or copy number data alone." (PMID 26501111, 2015).
acute lymphoblastic leukemia (1 paper, 2024). Leukemia with an acute onset, characterized by the presence of lymphoblasts in the bone marrow and the peripheral blood. "Familial 46, XY Disorder of Sexual Development (DSD) was discovered in a Ph+, BCR::ABL1P210+ Acute Lymphoblastic Leukemia (ALL) female with RCBTB2::LPAR6 fusion gene." (PMID 39091920, 2024).
lipoma (1 paper, 2024). A benign, usually painless, well-circumscribed lipomatous tumor composed of adipose tissue. "Therefore, genes known to be related to lipomas were also considered as potential candidate genes, and included SPRYD7, LHFPL6, RCBTB2, RCBTB1, and CDK4." (PMID 39719593, 2024).
liver cancer (1 paper, 2021). An epithelial or non-epithelial malignant neoplasm that arises from the liver. "For lung cancer, GMPS, EPHA10, C10orf54, and MAGEA6 are highly expressed in different subtypes; for liver cancer, CMYA5, DEPDC6, FAU, VPS24, RCBTB2, LOC100133469, and SLC35B4 are significantly expressed in different subtypes." (PMID 33747053, 2021).
lymphocytic leukemia (1 paper, 2024). "Chronic lymphocytic leukemia deletion gene 7(CLLD7) orRCC1 and BTB domain-containing protein 1(RCBTB1) andchromosome condensation 1-like(CHC1L) orRCC1 and BTB domain-containing protein 2(RCBTB2) are potential tumor suppressor genes located at 13q14.3 telomeric toRB1." (PMID 37311552, 2024).
spindle cell lipoma (1 paper, 2025). A benign circumscribed tumor composed of spindled cells, adipocytes, and collagen bundles. "At the molecular level, ASCPLT shares RB1 loss with spindle cell lipoma but typically harbors additional deletions, such as RCBTB2 loss." (PMID 41246635, 2025).
Stillbirth (1 paper, 2020). Death of the fetus in utero after at least 22 weeks of gestation. "Circulating NR4A2, EMP1, and RCBTB2 mRNA were differentially regulated in another cohort destined for stillbirth, compared to ongoing pregnancies." (PMID 32438913, 2020).
tumor (3 papers, 2012 to 2024). "Of note, the RB1 tumor suppressor gene coded at chromosome 13q14.2 was homozygous deleted together with the RCBTB2 gene in only one tumor (G97) from our series." (PMID 23029397, 2012).
RCBTB2 also shares sentences with these, for which no sentence is quoted: cancer (2 papers); multiple myeloma (2); lipomatous tumors (1); lung carcinoma (1); oral squamous cell carcinoma (1); prostate tumors (1); Zinc deficiency (1).